GPRC6A (G protein-coupled receptor class C group 6 member A)
Description:
Receptor activated by multiple ligands, including osteocalcin (BGLAP), basic amino acids, and various cations. Activated by amino acids with a preference for basic amino acids such as L-Lys, L-Arg and L-ornithine but also by small and polar amino acids. The L-alpha amino acids respond is augmented by divalent cations Ca(2+) and Mg(2+) (By similarity). Seems to act through a G(q)/G(11) and G(i)-coupled pathway (By similarity). Regulates testosterone production by acting as a ligand for uncarboxylated osteocalcin hormone: osteocalcin-binding at the surface of Leydig cells initiates a signaling response that promotes the expression of enzymes required for testosterone synthesis in a CREB-dependent manner (By similarity). Mediates the non-genomic effects of androgens in multiple tissue (By similarity). May coordinate nutritional and hormonal anabolic signals through the sensing of extracellular amino acids, osteocalcin, divalent ions and its responsiveness to anabolic steroids.
Synonyms: bA86F4.3; GPCR
Tractability: Small molecule: it belongs to a druggable protein family. Antibody: its Gene Ontology location is reachable by antibodies, with high confidence; UniProt places it where antibodies can reach, with medium confidence; UniProt predicts a signal peptide or a membrane-spanning region.
Target class: Family C G protein-coupled receptor; Membrane receptor
Gene: Protein-coding gene on chromosome 6 (116,792,085 to 116,829,083, reverse strand). Ensembl gene ENSG00000173612.
Subcellular location: Cell membrane
Pathways (Reactome):
Signal Transduction: Class C/3 (Metabotropic glutamate/pheromone receptors); G alpha (q) signalling events
Gene Ontology:
Molecular function: protein binding; G protein-coupled receptor activity; G protein-coupled peptide receptor activity
Biological process: response to amino acid; regulation of testosterone biosynthetic process; adenylate cyclase-activating G protein-coupled receptor signaling pathway; G protein-coupled receptor signaling pathway; positive regulation of insulin secretion involved in cellular response to glucose stimulus
Cellular component: plasma membrane; cell surface; membrane
Genetic constraint (gnomAD): Loss-of-function variants: 37 observed, 34.22 expected, observed/expected ratio (o/e) 1.08, 90% interval 0.83 to 1.42. The upper end of that interval is the gene's LOEUF score, 1.42, which puts it in group 5 of 6, group 1 being the genes least tolerant of losing a copy. Missense variants: 1,012 observed, 1,051.2 expected, observed/expected ratio (o/e) 0.96, 90% interval 0.91 to 1.01. Synonymous variants: 312 observed, 365.74 expected, observed/expected ratio (o/e) 0.85, 90% interval 0.78 to 0.94.
Homologues: Orthologues: chimpanzee GPRC6A (99% identical), macaque GPRC6A (96% identical), dog GPRC6A (87% identical), pig GPRC6A (86% identical), rabbit GPRC6A (84% identical), mouse Gprc6a (80% identical), rat Gprc6a (80% identical), tropical clawed frog gprc6a.2 (54% identical), zebrafish gprc6a (39% identical). Paralogues in human: CASR (31% identical), TAS1R3 (26% identical), TAS1R2 (25% identical), TAS1R1 (25% identical).
Diseases named in the same sentence as GPRC6A in open-access papers:
GPRC6A is named in the same sentence as 38 diseases in open-access papers, as found by Europe PMC text mining. Sharing a sentence is not in itself a finding about the gene and the disease. The quoted sentences say what the papers report.
prostate carcinoma (22 papers, 2012 to 2025). A carcinoma that arises from epithelial cells of the prostate gland. "CRISPR/Cas9 mediated GPRC6A deficient PC-3 xenograft cells showed reduced tumor growth and osteocalcin-associated progression of prostate cancer as compared to GPRC6A expressing PC-3 cells." (PMID 34899292, 2021). "We also examined by real-time PCR the effects of ligand stimulated GPRC6A on a panel of genes known to be associated with prostate cancer progression." (PMID 28659174, 2017). "Third, human genome wide association studies (GWAS) link single nucleotide polymorphisms (SNPs) in the GPRC6A locus with the development of prostate cancer in the Japanese, and Chinese population." (PMID 28659174, 2017). "For prostate cancer (all cases) the third strongest association result was for a common NS coding variant (rs2274911) in GPRC6A that is in very high LD with the known intronic GWAS variant rs339331." (PMID 23555315, 2013). "Importantly, GPRC6A-deficient prostate cancer cell line PC-3 created by CRISPR/Cas9 technology demonstrates drastically lower growth and aggression than nonmanipulated cells in vitro and in vivo." (PMID 35508982, 2022). "In addition, clinical and in vitro data revealed that GPRC6A is associated with aggressive prostate cancer, with a pivotal role in cell proliferation, migration, invasion, and Epithelial-Mesenchymal Transition (EMT)." (PMID 34831222, 2021). "GPRC6A is a G-protein coupled receptor that senses nutrition and is activated in vitro by several ligands like amino acids, calcium, zinc, osteocalcin (OC), and testosterone and has been implicated in prostate cancer." (PMID 32765953, 2020). "More recently, the SNP rs1606365 GPRC6A was found to be associated with aggressive prostate cancer." (PMID 28659174, 2017). "GPRC6A may provide a molecular basis for the association between Metabolic Syndrome and the risk of prostate cancer." (PMID 28659174, 2017). "GPRC6A activation could stimulate prostate cancer cell proliferation and chemotaxis, while GPRC6A deficiency retarded tumor progression and improved survival in prostate cancer mouse model." (PMID 25257522, 2014). "This suggests the RFX6 gene variation may be the susceptibility loci underlying the observed association signal of the GPRC6A/RFX6 loci with prostate cancer in the original GWAS." (PMID 22662242, 2012). "In xenograft models of prostate cancer, cells expressing GPRC6A promoted cell migration and proliferation after stimulation with osteocalcin via ERK and AKT signalling, in comparison to knockout cells." (PMID 39982274, 2025). "GPRC6A transcripts are upregulated in prostate cancer, and in prostate cell lines, with ligands to GPRC6A such as calcium and arginine showing a dose-dependent stimulation of ERK activity as well as chemotaxis and proliferation." (PMID 39982274, 2025). "GPRC6A as a G-protein binding receptor modulated prostate cancer progression is known to be activated by testosterone." (PMID 37991884, 2024). "OC has also been found to facilitate the growth and migration of lung tumors through neutrophil aggregation and to induce the growth of prostate cancer cells via G protein-coupled receptor family C group 6 member A (GPRC6A) receptor." (PMID 36926025, 2023). "Conversely, ablation of GPRC6A in prostate cancer mice xenografts resulted in decreased tumor progression and enhanced survival." (PMID 34831222, 2021). "Noteworthy, compared to normal prostate cells, GPRC6A upregulation was observed in different prostate cancer cell lines, where its activation led to an increase in chemotaxis and cell proliferation in vitro." (PMID 34831222, 2021). "Further in a human xenograft model, CRISPR-Cas9 targeting of GPRC6A suppresses prostate cancer tumorigenesis." (PMID 32765953, 2020).
prostate carcinoma (continued). "In recent years TRPM8 (transient receptor potential cation channel subfamily M member 8) and GPRC6A (G protein-coupled receptor class C group 6 member A) proteins were demonstrated to mediate the action of androgens in prostate cancer cells." (PMID 33167316, 2020). "Using a panel of human prostate cancer cell lines, we confirmed that human GPRC6A transcripts are expressed in all prostate cancer cell lines tested." (PMID 28659174, 2017). "A direct role of GPRC6A in the pathogenesis of human prostate cancer, however, remains to be established with certainty." (PMID 28659174, 2017). "In the current study, we examined the function of human GPRC6A in prostate cancer progression in vitro and in vivo." (PMID 28659174, 2017). "We also tested the effects of GPRC6A activation on testosterone biosynthesis in prostate cancer cells." (PMID 28659174, 2017). "The effect of editing GPRC6A on prostate cancer growth and progression in vivo was assessed in a Xenograft mouse model implanted with wild-type and PC-3 deficient cells and treated with the GPRC6A ligand osteocalcin." (PMID 28659174, 2017). "Human GPRC6A is a functional osteocalcin and testosterone sensing receptor that promotes prostate cancer progression." (PMID 28659174, 2017). "First, GPRC6A is increased in human prostate cancer cell lines and in a subset of human prostate cancer tumors." (PMID 28659174, 2017). "Second, activation of GPRC6A stimulates cell proliferation and chemotaxis in human prostate cancer cells, and promotes prostate cancer epithelial-mesenchymal transition, whereas knockdown of GPRC6A inhibits prostate cancer cell migration and invasion." (PMID 28659174, 2017). "Available evidence suggests that GPRC6A and its ligands modulate the progression of prostate cancer." (PMID 28659174, 2017). "We previously demonstrated that GPRC6A can directly promote prostate cancer cell proliferation, migration, and in vivo tumor growth." (PMID 28659174, 2017). "Prostate specific antigen and Runt-related transcription factor 2 (RUNX2), a bone-specific transcriptional regulator expressed in metastatic prostate cancer cells, are regulated by ligand activation of GPRC6A." (PMID 28659174, 2017). "Taken together, our findings support a role for GPRC6A and osteocalcin in prostate cancer, and define a potential therapeutic target to suppress prostate cancer progression." (PMID 28659174, 2017). "We also used clustered regularly interspaced short palindromic repeats (CRISPR) and CRISPR-associated protein 9 nuclease (Cas9) (CRISPR/Cas9) to disrupt the GPRC6A gene in the human prostate cancer cell line (PC-3)." (PMID 28659174, 2017). "Finally, the persistence of the ancestral RKLP sequence and its predominant expression in humans of African descent suggest that this human polymorphism may contribute to the racial disparities in diseases associated with GPRC6A, including Metabolic Syndrome and prostate cancer." (PMID 28659174, 2017). "GPRC6A is also coupled to signaling pathways, such as phosphatidylinositol 3-kinase that are known to be deregulated in prostate cancer." (PMID 25502083, 2015). "The related genes, C2orf43, FOXP4, GPRC6A and RFX6, are warranted for further efforts to determine the functional variations and finally to clarify the genetic mechanism of susceptibility to prostate cancer." (PMID 22662242, 2012). "Our results provide further support for association of the C2orf43, FOXP4, GPRC6A and RFX6 genes with prostate cancer in Eastern Asian populations." (PMID 22662242, 2012). "GPRC6A is an orphan GPCR that has recently gained attention for its role in prostate cancer." (PMID 39982274, 2025). "Although it induces the EMT process of prostate cancer, KD of GPRC6A attenuates such cell invasion." (PMID 35508982, 2022).
prostate carcinoma (continued). "For example, the G-protein–coupled receptor GPRC6A is located in multiple tissues, including gastrointestinal epithelia; studies have shown that GPRC6A is involved in regulating glucose and fat metabolism in certain cancers such as prostate cancer progression." (PMID 36046250, 2022). "The tumorigenic effects of GPRC6A have been widely studied in prostate cancer." (PMID 37435447, 2022). "In addition, GPRC6A promotes prostate cancer cell proliferation and migration by activating ERK and mTOR phosphorylation in response to testosterone and osteocalcin." (PMID 37435447, 2022). "GluOC has also been found to induce the growth of prostate cancer cells through GPRC6A." (PMID 35413833, 2022). "In addition, GPRC6A deficient PC-3 xenografts exhibited significantly less growth and were resistant to osteocalcin-induced prostate cancer progression compared to control PC-3 cells expressing GPRC6A." (PMID 28659174, 2017). "Osteocalcin activation of GPRC6A may indirectly promote androgen synthesis through stimulation of IL-6, a cytokine that can promote androgen synthesis in prostate cancer cells through enhancing AKR1C3 transcription." (PMID 28659174, 2017). "In this study we tested if human GPRC6A has important tumor promoting effects in prostate cancer." (PMID 28659174, 2017). "As such, GPRC6A is “a target of interest” for treating prostate cancer and warrants further efforts to develop antagonists for this receptor as potential treatments for prostate cancer." (PMID 28659174, 2017). "Finally, we found that GPRC6A mediates prostate cancer progression in vivo by assessing the response to osteocalcin in human prostate cancer xenograft models of cells expressing endogenous GPRC6A or with CRISPR/Cas9 mediated deletion of GPRC6A." (PMID 28659174, 2017). "There is emerging evidence that GPRC6A is involved in the pathogenesis of prostate cancer." (PMID 28659174, 2017). "Because of questions regarding the cell surface expression of GPRC6A, and the importance of the 3rd intracellular loop (3rd IL) in GPCR membrane trafficking, we sequenced this region in DU145, PC-3, LNCap and 22Rv1 human prostate cancer cell lines." (PMID 28659174, 2017). "In addition, activation of GPRC6A can stimulate androgen biosynthesis pathways to regulate intra-tumoral steroidogenesis in prostate cancer cells, and in testicular Leydig cells to stimulate circulating testosterone concentrations." (PMID 28659174, 2017). "GPRC6A may contribute to racial disparities in prostate cancer, and is a potential therapeutic target to develop antagonists to treat prostate cancer." (PMID 28659174, 2017). "In addition, activation of GPRC6A stimulated prostate cancer cell line proliferation and migration, whereas editing GPRC6A in PC-3 cells reduced cell proliferation and transcription of PCNA and c-Fos." (PMID 28659174, 2017). "We assessed the effects of GPRC6A on prostate cancer growth and cell migration." (PMID 28659174, 2017). "Finally, to investigate the effects of GPRC6A on regulation of prostate cancer cell progression in vivo, we performed human xenograft studies in nude mice." (PMID 28659174, 2017). "On all accounts, nearly all researches about GPRC6A associated with cancer focused on prostate cancer, no investigation about this gene on ovarian cancer has been published." (PMID 25502083, 2015). "Increments in Gprc6a may augment the ability of prostate cancer cells to proliferate in response to dietary- and bone-derived ligands." (PMID 25938513, 2015). "GPRC6A is expressed at higher levels in human prostate cancer cells and prostate cancer tissues and small interfering RNA knockdown of GPRC6A attenuates these response in human prostate cancer cell lines." (PMID 25502083, 2015). "In respect to diseases, GPRC6A was upregulated in various prostate cancer cell lines." (PMID 25257522, 2014).
prostate carcinoma (continued). "Notably, around the loci of the GPRC6A and RFX6 genes, the SNPs significantly associated with prostate cancer narrowed to the region of the RFX6 gene, compared to a wide distribution of significantly associated SNPs across the whole region of these two genes in the original GWAS." (PMID 22662242, 2012). "GPRC6A expression levels are higher in VCaP and PC3 prostate cancer cells compared with expression levels in RWPE-1 normal prostate cells." (PMID 37435447, 2022). "Also, cancer cells may be targeted by the CRISPR-Cas9 system, with knockouts of Par3L, Src-1, and GPRC6A ameliorating colorectal, breast, and prostate cancer respectively, resulting in increased sensitivity to chemotherapeutics, lower proliferation, and higher cancer cell death." (PMID 32765953, 2020). "The current study shows that by activating GPRC6A, signaling via ERK, AKT, and mTOR is increased in prostate cancer cells." (PMID 28659174, 2017). "We successfully replicated the association of rs13385191 (located in the C2orf43 gene, P = 8.60×10−5), rs12653946 (P = 1.33×10−6), rs1983891 (FOXP4, P = 6.22×10−5), and rs339331 (GPRC6A/RFX6, P = 1.42×10−5) with prostate cancer." (PMID 22662242, 2012). "In addition to AP-1, G protein-coupled receptor family C group 6 member A (GPRC6A) as a functional osteocalcin and testosterone sensing receptor contributes to prostate cancer growth." (PMID 35508982, 2022). "Furthermore, knocking out Gprc6a using CRISPR/Cas9 technology abolished osteocalcin-mediated activation of ERK, AKT, mTOR signaling and cell proliferation in human prostate cancer xenograft models." (PMID 30687236, 2018). "Also the G –protein –coupled receptor family C group 6 member A (GPRC6A) has been shown to mediate androgen actions independent of DNA binding and to mediate testosterone induced ERK phosphorylation in prostate cancer cells." (PMID 30416486, 2018). "GPRC6A is not identified in gene expression signatures that predict prostate cancer disease severity in humans." (PMID 28659174, 2017). "GPRC6A edited PC-3 cells exhibited an attenuated response to L-Arg, osteocalcin and testosterone stimulation of ERK, Akt, and mTOR phosphorylation compared to controls, pathways involved in advanced prostate cancer and emergence of hormone-refractory disease." (PMID 28659174, 2017). "Our findings also suggest that GPRC6A, by mediating the non-genomic effects of testosterone, may provide alternative pathways to androgen receptor signaling in prostate cancer." (PMID 28659174, 2017). "Indeed, testosterone binding to GPRC6A has been demonstrated to activate ERK, Akt and mammalian Target of Rapamycin (mTOR) signaling pathways in a time and dose-dependent manner, resulting in an increased cell proliferation and inhibition of autophagy in prostate cancer cells." (PMID 34831222, 2021). "Finally, GPRC6A mediates the non-genomic, rapid signaling responses to testosterone, leading to activation of PI3K/Akt pathways that are implicated in androgen receptor (AR)-independent progression and therapeutic resistance of prostate cancer." (PMID 28659174, 2017).